RN7SL395P (RNA, 7SL, cytoplasmic 395, pseudogene)
Gene: Miscellaneous RNA gene on chromosome 8 (144,785,298 to 144,785,588, forward strand). Ensembl gene ENSG00000244307.
Homologues: Orthologues: chimpanzee Metazoa_SRP (97% identical), macaque Metazoa_SRP (91% identical). Paralogues in human: RN7SL1 (86% identical), RN7SL2 (86% identical), RN7SL3 (85% identical), RN7SL230P (83% identical), Metazoa_SRP (82% identical), RN7SL126P (82% identical), RN7SL357P (82% identical), RN7SL575P (82% identical), RN7SL333P (82% identical), RN7SL627P (82% identical), RN7SL122P (81% identical), RN7SL296P (81% identical), and 702 more.